INS (insulin)
Diseases named in the same sentence as INS in open-access papers (continued):
Sharing a sentence is not in itself a finding about the gene and the disease.
dyslipidaemia (172 papers, 2007 to 2026). "In diabetic patients, inadequate insulin levels contribute to a decrease in the activity of enzymes that are associated with lipid metabolism, leading to dyslipidaemia." (PMID 38273354, 2024). "Mutations in ADCY3 in mice cause impaired insulin sensitivity and dyslipidaemia and mice with ADCY3 knockout show increased fat mass, hyperphagia, depression-like phenotypes, and leptin resistance." (PMID 37368776, 2023). "Reducing VF ameliorates dyslipidaemia and stimulates efflux of immune cells thereby improving insulin sensitivity and metabolic risk factors." (PMID 36225127, 2022). "The ketogenic diet has gained much popularity over the years due to its effects on promoting weight loss, increasing insulin sensitivity and reducing dyslipidaemia." (PMID 35011071, 2021). "It was reported that traditional cigarettes cause dyslipidaemia, increase the inflammatory mediator and decrease insulin sensibility." (PMID 32818031, 2020). "Specifically, adiponectin can have beneficial effects on lipid metabolism because of its insulin-sensitizing effects, whereas IL-6 has been involved in the dysregulation of insulin signalling and has been associated with dyslipidaemia." (PMID 27567677, 2016). "In contrast, large adipocytes are associated with dyslipidaemia, glucose and insulin abnormalities, are insulin resistant and are prone to necrosis and inflammation." (PMID 26067361, 2015). "Subsequent guidelines and expert consensus have recognised the importance of atherogenic dyslipidaemia as a key driver of CV risk in insulin-resistant states, even if LDL cholesterol levels are well controlled." (PMID 24460800, 2014). "The novelty of our study lies in the comparison of four markers of cardiovascular risk: dyslipidaemia [lp(a)], insulin reistance (leptin), inflammation (hs-CRP) and matrix remodelling (PAPP-A), as possible predictors of plaque instability." (PMID 22836155, 2012). "Emerging research suggests that aerobic exercise may have a positive impact on various mechanisms known to be associated with elevated cancer risk, such as improving insulin sensitivity, mitigating systemic inflammation and addressing dyslipidaemia." (PMID 39618343, 2024). "Meanwhile, skeletal muscle is regarded as an essential insulin-responsive endocrine organ, and muscle loss worsens glycemic control and insulin sensitivity, which may facilitate the onset of dyslipidaemia." (PMID 36123675, 2022). "Instead, fat distribution is a critical determinant of insulin sensitivity, specifically when fat is stored around visceral areas, which is associated with hepatic insulin resistance, dyslipidaemia and impairments in insulin-mediated peripheral glucose disposal." (PMID 34220720, 2021). "The release of free fatty acids from visceral fat into the portal vein that directly leads to the liver may cause reduced hepatic insulin clearance, increased gluconeogenesis and increased dyslipidaemia that manifests as increased 2h-PCPG." (PMID 20459710, 2010). "Their findings, based on 59 cohort studies, reinforce the notion that dyslipidaemia—particularly elevated triglycerides—parallels worsening insulin sensitivity and metabolic control in prediabetic individuals." (PMID 41178702, 2026). "L. reuteri J1 inhibits weight gain, reduces adiposity, attenuates dyslipidaemia, and improves glucose homeostasis and insulin sensitivity in obese mice." (PMID 41395840, 2025). "However, the lack of FPI improvement with orforglipron warrants caution, as suppressed insulin levels in the context of weight loss may paradoxically exacerbate dyslipidaemia in susceptible individuals – a phenomenon observed in certain lifestyle intervention trials." (PMID 41450584, 2025). "Pdgfrα-cre driven KO of Alms1 (MSC KO) recapitulated insulin resistance, fatty liver, and dyslipidaemia in both sexes." (PMID 38583571, 2024). "Simultaneously, dyslipidaemia induces insulin resistance, impaired insulin secretion, and β-cell apoptosis." (PMID 38273354, 2024).
dyslipidaemia (continued). "These men had more visceral and intramuscular fat, and signs of dyslipidaemia, low-grade inflammation, and adipose tissue insulin resistance prior to undertaking intense exercise for 12 weeks." (PMID 38921470, 2024). "MET has been shown to improve dyslipidaemia by enhancing insulin sensitivity and regulating hepatic lipid metabolism." (PMID 39596174, 2024). "These targets would be attainable with intensive insulin treatment (69.3% vs. 67.5%) and a high-rate usage of statin (76.8% vs. 73.3%)—or with dyslipidaemia therapy (78.6% vs. 78.6%)—during follow-up treatment in Beijing and Taiyuan." (PMID 37408009, 2023). "Two clinical studies looked at the benefit of cumin on anthropometric measures, blood insulin and blood lipid levels in overweight adults and women with dyslipidaemia." (PMID 38068725, 2023). "Dyslipidaemia: IR results in enhanced hepatic flux of fatty acids originating from the diet and resistance to the antilipolytic effects of insulin within adipose tissue." (PMID 33430419, 2021). "Earlier studies in mice have shown dyslipidaemia to be a factor contributing to the apoptosis of pancreatic β-cells, to insulin biosynthesis, defective insulin secretion, and altered glucose metabolism." (PMID 33670226, 2021). "BRS reversed dyslipidaemia, controlled blood glucose stability, improved insulin sensitivity, and maintained hormone homeostasis in HFD-induced rats; in particular, BRS dose and hormone level showed a dose-effect relationship." (PMID 33585429, 2021). "A recent study used genome-wide SNP data to estimate heritability of several traits known to be perturbed by EMS (glucose, insulin, measures of insulin sensitivity, and dyslipidaemia) and found they were moderately to highly heritable." (PMID 33233816, 2020). "Insulin has also been shown to directly increase the degradation of apoB which ameliorates dyslipidaemia." (PMID 29975702, 2018). "Dyslipidaemia is one of the very early features of an obese or MetS phenotype and frequently precedes metabolic disturbances in insulin and glucose homeostasis." (PMID 23306188, 2013). "The second subset corresponded to the MAO patients, a group that displayed the typical dyslipidaemia seen in insulin resistant patients." (PMID 22413940, 2012). "It has been shown to improve dyslipidaemia, insulin sensitivity, and the immune response to antigens." (PMID 21599899, 2011). "This may be because females typically possess less fat-free muscle mass compared to males, potentially exacerbating insulin resistance and dyslipidaemia." (PMID 41237094, 2025). "This was accompanied by impaired insulin utilisation, hyperinsulinaemia, and dyslipidaemia." (PMID 41141342, 2025). "One of the first in vivo evidence linking dyslipidaemia with impaired β-cell function was observed in hyperglycaemic Goto-Kakizaki rats, where the hyperlipidaemia induced by high-fat feeding markedly impaired glucose-induced insulin secretion in this model." (PMID 38642584, 2024). "The reduction in dyslipidaemia may possibly be attributed to its antihyperglycaemic and anti-inflammatory properties, along with an increase in insulin production from pancreatic β-cells." (PMID 37371821, 2023). "The lipid metabolism is commonly deranged in diabetic conditions due to lack of insulin to regulate the synthesis and breakdown of lipid in adipose tissues, thereby causing dyslipidaemia leading to atherosclerosis." (PMID 37528147, 2023). "Disrupted glucose-insulin homeostasis may pre-date the onset of psychosis, and clinically-relevant insulin resistance and dyslipidaemia are detectable from the onset of psychosis in relatively young antipsychotic naïve patients." (PMID 36039146, 2022). "At 120 min after the glucose challenge, FDRs and dysglycaemic subjects had higher glucose and insulin levels compared to normoglycaemic subjects after adjustment for age, sex, dyslipidaemia, smoking, BMI, waist and hip circumferences and systolic and diastolic blood pressure (p < 0.05)." (PMID 35743370, 2022).
dyslipidaemia (continued). "The dyslipidaemia observed in the DC group who did not receive polyphenol supplementation was most likely due to the deficiency of circulating insulin, which increases lipase activity and fatty acid mobilisation from adipose tissue." (PMID 34201794, 2021). "Indeed, in our study, dyslipidaemia parameters (triglycerides, LDL-C, and HDL-C), glucose homeostasis (HbA1c, fasting glucose, and insulin), SBP, age, and gender (men) were associated with increased gamma GT levels." (PMID 32566678, 2020). "Fatty liver and atherogenic dyslipidaemia are major sources of IR-related morbidity, so investigating how these are dissociated from IR in the face of proximal insulin signalling defects will potentially reveal novel approaches to mitigate IR-associated disease." (PMID 32439336, 2020). "The clinical variables that predicted higher HbA1c were dyslipidaemia, having diabetic end‐organ failure, taking insulin medication only and taking both oral medication and insulin which in part may be a proxy for greater T2D and HF disease severity." (PMID 32802365, 2020). "It is also likely that in vivo, abnormal glucose metabolism is not the sole cause of aberrant lipid metabolism within the placenta and that maternal insulin levels and dyslipidaemia may also be an important determinant of placental fatty acid metabolism." (PMID 31575970, 2019). "Additional guidelines for insulin therapy and dyslipidaemia were recently published." (PMID 24299164, 2013). "Thus, further studies are needed to clarify the role of hyperinsulinaemia and dyslipidaemia in insulin secretion in humans." (PMID 17257277, 2007). "We also found a potential causal link between blood levels of BCAAs and lipid profiles, proposing that BCAAs, such as leucine, could activate the mTOR signalling pathway in a manner distinct from insulin, suggesting that BCAAs may directly affect lipid metabolism and contribute to dyslipidaemia." (PMID 38711861, 2024). "The insulin sensitivity of muscle tissue is also reduced by the excessive level of fatty acids due to the inhibition of glucose uptake, both from the mobilization of body fat and the presence of dyslipidaemia (low HDL-c and TC, LDL-c, VLDL-c and high triglycerides)." (PMID 28492722, 2017). "However, in subcutaneous mature adipocytes from severely obese humans, FAAH and MGL enzyme activities are not altered in relation to BMI, waist circumference, adipose tissue distribution, blood pressure, fasting glucose or insulin, glycaemic control or dyslipidaemia." (PMID 24593280, 2014). "However, emerging evidence suggests that improving insulin sensitivity, modifying systemic inflammation, controlling dyslipidaemia and decreasing adipose tissue are potential mechanisms whereby physical activity may contribute to reduced risk for certain cancers." (PMID 39618343, 2024). "Patients with CKD tended to use insulin, renin–angiotensin–aldosterone system (RAAS) inhibitors, sodium-glucose cotransporter-2 inhibitors (SGLT-2i) and dyslipidaemia therapy in Taiyuan than in Beijing." (PMID 37408009, 2023). "Non-responders showed more visceral and intramuscular fat and signs of dyslipidaemia and low-grade inflammation at baseline and did not improve in insulin sensitivity following exercise, although they showed gains in VO2max and muscle strength." (PMID 38921470, 2024). "Intensive insulin therapy and personal nutritional guidance, along with the extensive use of RAAS inhibitors, SGLT-2i and dyslipidaemia therapy during follow-up, can all play a positive role in the management of CKD in patients with T2DM in both Beijing and Taiyuan." (PMID 37408009, 2023). "In contrast, primary insulin signalling defects (in INSR or PIK3R1) do not result in dyslipidaemia or fatty liver." (PMID 35234134, 2022). "In contrast, humans with severe IR due to proximal insulin signalling defects do not have the dyslipidaemia, fatty liver, nor decreased plasma adiponectin concentration usual in common IR." (PMID 32439336, 2020).
dyslipidaemia (continued). "Further, when children were stratified by the presence of dyslipidaemia based on serum TAG concentrations or HDL-cholesterol concentrations, HOMA-IR and insulin concentrations were higher in the children with high serum TAG and low serum HDL cholesterol concentrations." (PMID 27534260, 2016). "A balanced n-6/n-3 ratio, with the n-3 fatty acids provided as EPA and DHA, alters metabolic pathways and modulates gene expression resulting in better insulin sensitivity, lower dyslipidaemia and hepatic TAG without increasing oxidative stress." (PMID 25837985, 2015). "The improvement in insulin sensitivity following intake of flaxseed mucilage wasaccompanied by reductions in markers for inflammation and dyslipidaemia, although thesechanges were non-significant, compared with the placebo group." (PMID 26134388, 2015). "Maternal manganese restriction increased the susceptibility of the offspring to high-fat-induced adiposity, dyslipidaemia, and a proinflammatory state but did not affect their glycemic or insulin status." (PMID 22007189, 2011). "Furthermore, one cannot overlook the probable effects of dyslipidaemia observed in HF/DDE animals, which, through lipotoxic events in insulin-responsive organs, may contribute to a reduction in peripheral insulin response." (PMID 28572628, 2017). "We thus hypothesised that in SHORT syndrome, the liver is protected from increased insulin-mediated lipogenesis, which is relatively unaffected by common IR, and that this explains the absence of dyslipidaemia and fatty liver despite severe IR and lipodystrophy." (PMID 32439336, 2020). "Finally, in adolescents with uncontrolled T1DM, continuous subcutaneous insulin infusion could improve glycemia, but only glycemic control may be unlikely to normalize dyslipidaemia and subsequent potential cardiac dysfunction." (PMID 32708413, 2020).
Hypercholesterolemia (172 papers, 2001 to 2026). An increased concentration of cholesterol in the blood. "HDAC11 deficiency enhances glucose tolerance and insulin sensitivity, attenuates liver damage, hepatosteatosis and hypercholesterolemia by boosting energy expenditure through promoting thermogenic capacity." (PMID 36339432, 2022). "Hypercholesterolemia has detrimental effects on insulin secretion and even causes islet cell apoptosis when oxidative LDLc is taken up via LDL receptors." (PMID 24966876, 2014). "Krysiaket al. suggest that insulin-resistant patients with hypercholesterolemia and high cardiovascular risk may benefit the most from combined simvastatin and ezetimibe treatment." (PMID 36753488, 2023). "In humans, there is evidence that maternal hypercholesterolaemia is associated with the development of fatty streaks in fetal arteries, and cholestasis during pregnancy is associated with programming of an overweight, insulin-resistant phenotype in humans." (PMID 27777632, 2016). "In diabetic states, hypercholesterolemia arises because insulin inhibits β-hydroxy-β-methylglutaryl-coenzyme-A reductase an essential enzyme involved in cholesterol metabolism." (PMID 39822379, 2024). "Low-dose DHEA treatment enhanced vascular endothelial functionality and insulin sensitivity while decreasing plasminogen activator inhibitor type 1 concentration in a randomized, double-blind investigation of men with hypercholesterolemia." (PMID 38075062, 2023). "The hyperglycemic status increased de novo lipogenesis, in turn, TG acted as the substrate to promote endogenous glucose production, hypercholesterolemia was also related to the prolonged increase in insulin levels." (PMID 35860700, 2022). "Results showed that offspring from the LP group exhibited hypercholesterolemia, impaired hepatic insulin sensitivity, increased serum insulin level, and liver fat accumulation, as compared to NP group, in response to HFD." (PMID 36235710, 2022). "Our results indicate Yarrow SFE improves circulating fasting glucose levels, enhances insulin sensitivity, and diminishes hypertriglyceridemia and hypercholesterolemia." (PMID 31888081, 2019). "Results indicate improved fasting glucose levels in plasma, enhanced insulin sensitivity, and diminished hypercholesterolemia in the HFD + Yarrow group compared to the HFD group." (PMID 31888081, 2019). "MUNW encompasses glucose elevation in the presence of impaired insulin secretion, hypercholesterolemia, low leg fat mass, visceral obesity and fatty liver." (PMID 31673340, 2019). "Hypercholesterolemia also contributes to decreased insulin production and pancreatic beta cell dysfunction." (PMID 30212478, 2018). "Hypercholesterolemia develops in the diabetic state because insulin has an inhibitory action on β-hydroxy-β-methylglutaryl-Coenzyme-A (HMG-CoA) reductase, a key rate-limiting enzyme responsible for the metabolism of cholesterol-rich LDL particles." (PMID 30323764, 2018). "In animal studies, high intracellular concentration of cholesterol is known to affect insulin secretory process, and hypercholesterolemia impairs insulin secretion in LDL receptor knockout mice." (PMID 28510610, 2017). "This review focuses on the potential link between insulin and endoplasmic reticulum stress, hypercholesterolemia, and angiogenesis in GDM in the human fetoplacental vasculature." (PMID 27065887, 2016). "As expected, F1 males and females weaned onto the cafeteria diet showed increased weight gain, glucose-insulin dyshomeostasis and hypercholesterolaemia." (PMID 25082159, 2014). "It has been reported that simvastatin significantly increased insulin and leptin levels in patients with hypercholesterolemia." (PMID 24255692, 2013). "It is shown to reduce glycemia, insulin index, hypercholesterolemia, oxidative stress, HbA1c, PAI-1, and tumor necrosis factor alpha." (PMID 23304216, 2012).